TNF (tumor necrosis factor)
Diseases named in the same sentence as TNF in open-access papers (continued):
Sharing a sentence is not in itself a finding about the gene and the disease.
Obesity (continued). "Obesity-associated HCC development depended on the increased tumor-promoting cytokines IL-6 and TNF, inducing liver inflammation and activation of oncogenic signal transducer and activator of transcription 3 (STAT3) signaling in mice." (PMID 35002979, 2021). "Visfatin synthesis increases in obesity and stimulates the expression of inflammatory cytokines such as IL-6 and TNF-α, adhesion molecules, metalloproteinases (MMP-2 and MMP-9), VSMCs proliferation and migration, and collagen synthesis." (PMID 34202323, 2021). "Febuxostat, an XOD inhibitor, attenuates stress-induced hyperuricemia and inflammatory parameters, including TNF-α mRNA expression in the adipose tissue, indicating the involvement of uric acid in obesity-related inflammation." (PMID 34961109, 2021). "Leptin, an important secretory product of adipocytes that is increased in obesity, has important proinflammatory actions on the secretion of cytokines (TNFα, IL-1, IL-6) and on innate and adaptive immune cells." (PMID 34359821, 2021). "Obesity is associated with increased inflammation in adipose tissue, with monocyte chemoattractant protein 1 (MCP-1), IL-6, toll-like receptor 4 (TLR4), and TNFα elevated in adipose tissue of obese relative to lean individuals." (PMID 34149621, 2021). "As well, TNF-α and IL-6 knockout mouse models have shown positive energy balance, suggesting that energy accumulation, observed in obesity, induces chronic inflammation, which in turn, promotes energy expenditure as a compensatory mechanism." (PMID 34108550, 2021). "Obesity leads to a proinflammatory milieu characterized by increased levels of TNF-α, plasminogen activation inhibitor-1, angio-tensinogen, plasminogen activation inhibitor-1, IL-6, leptin, and decreased adiponectin levels which enhance endothelial functions." (PMID 34249177, 2021). "Enhanced expression of ANGPTL2 seems to be a response to the increased inflammation that accompanies obesity, such that TNFα and TGFβ that are increased in obesity directly increase gene expression of ANGPTL2." (PMID 34422408, 2021). "Recent studies have shown that diabetes, obesity and elevated levels of CRP, TNF-alpha and leptin are closely associated." (PMID 34923973, 2021). "Increased levels of both factors, IL-6 and TNF-α, have been diagnosed in people with obesity and osteopenia." (PMID 34279426, 2021). "TNF-α mRNA levels tended to be more strongly correlated with the presence of cardiovascular diseases (p = 0.0186), hypertension (p = 0.0438), and obesity (p = 0.0034)." (PMID 33995400, 2021). "The expression of TNFα in adipose tissue is elevated in a variety of experimental obesity models and obese humans, as well as in patients with HALS and cancer cachexia." (PMID 33872596, 2021). "To simulate the low‐level inflammatory response during obesity, we selected the TNF‐α concentration of 1 ng/ml for 5 days in the subsequent experiments." (PMID 34676967, 2021). "RASE1 suppressed NF-κB, pathway and proinflammatory cytokines IL-10, IL-6, and TNF-α level, which are involved in inflammation and progression of obesity." (PMID 34812408, 2021). "TNF-α and IL-1β play key roles in the obesity, T2D, and metabolic disorders, disrupting the insulin and lipid signaling pathways, thereby influencing insulin sensitivity and lipid metabolism." (PMID 34712684, 2021). "Once obesity induces the phenotype switch of ATMs, proinflammatory cytokines secreted by M1 ATMs, particularly TNF-α, IL-1 and IL-6, play a direct role in promoting insulin resistance and exacerbating local or systemic metabolic dysfunction." (PMID 34108967, 2021). "Bee bread (0.5 g/kg/day for 12 weeks) has been previously reported to suppress TNF-α and NF-κβ, and increase IL-10 levels in obesity-induced aortic vascular damage and HFD-induced renal damage rats." (PMID 34943134, 2021).
Obesity (continued). "High leptin levels in aging and obesity upregulate the proinflammatory cytokines IL-6 and TNF-α, reducing insulin-like growth factor 1 (IGF1) activity and decreasing their anabolic actions on skeletal muscle." (PMID 34676021, 2021). "We analysed the secretome of VAT and SAT based on the obesity status of the patient and found significantly higher levels of bFGF, Eotaxin-3, and TNF-α secreted from the VAT of obese patients than from that of non-obese patients." (PMID 34822426, 2021). "Obese adipocytes upregulate the expression of pro-inflammatory factors such as TNF-α and IL-6 through the obesity-inflammation-aromatase axis, resulting in enhanced transcription of CYP19 gene encoding aromatase, thereby promoting the production of aromatase." (PMID 33842335, 2021). "Curcumin has been demonstrated to significantly reduce the plasma levels of TNF-α and interleukin (IL)-6 and, subsequently, improves insulin sensitivity and decreases obesity-induced insulin resistance." (PMID 33669954, 2021). "This is further corroborated by the reduced IFN-γ and TNF-α production in stimulated polyclonal T cells from subjects with obesity." (PMID 34373739, 2021). "In the present study, the association between obesity indices (BMI, WC, and %BF), leptin and low‐grade inflammation (CRP, IL‐6, TNF‐α) in a Zanzibari population of individuals aged 5 years and above was investigated." (PMID 33680494, 2021). "Circulating TNF-α levels were analyzed in 14 studies in which 319 participants with overweight or obesity were involved in a training program." (PMID 34948868, 2021). "Obesity gradually promotes a chronic low-grade inflammatory state and adipocytes begin to secrete pro-inflammatory cytokines, such as TNF-α, increasing macrophages infiltration in the adipose tissue." (PMID 33652751, 2021). "According to several studies, in obesity and physical inactivity, dysfunctional adipocytes start secreting higher amounts of the pro-inflammatory cytokines IL-1 (α and β subtypes), TNF-α, and IL-6." (PMID 34436472, 2021). "HFD-induced obesity resulted in the increased secretion of several inflammatory cytokines such as TNF-α and IL-1β." (PMID 34960036, 2021). "Obesity correlates with elevated insulin levels, free IGFs, and adipocyte-derived factors, including leptin, the tumor necrosis factor-alpha (TNF-α), and interleukin-6 (IL-6)." (PMID 34298805, 2021). "TNF-α, Il-1β, IL-6 and IL-8 are involved both in the pathogenesis of HS as well as in the development of glucose intolerance, obesity, hyperlipidemia, metabolic syndrome and atherosclerosis." (PMID 34830597, 2021). "In obesity-related kidney disease, several adipokines have been implied such as leptin, adiponectin, tumor necrosis factor α (TNF-α) or interleukin 6 (IL-6)." (PMID 33928108, 2021). "Butyrate, when administered in db/db diabetic mice with obesity via the I.P. route (1 g/kg), reduced the mRNA expression of inflammatory cytokines (interleukin 1, interleukin 6, and tumor necrosis factor α) in adipose tissue." (PMID 33801984, 2021). "Previous reports indicated that MAPK1 contributes to the elevated secretion of monocyte chemoattractant protein-1 (MCP-1), and MAPK3 is associated with enhanced mRNA levels of inflammatory markers, such as CCL2, IL1β, and TNF-α in obesity." (PMID 34360840, 2021). "Inflammatory diseases, such as obesity, type 2 diabetes mellitus, and periodontitis induce the production of pro-inflammatory cytokines, such as Tumor Necrosis Factor alpha (TNF-α), IL-1, and IL-6, influencing the involvement and progression of each other." (PMID 33802889, 2021). "Growing evidence indicates that TNFα is a major mediator of inflammation in general, of insulin resistance and of obesity in particular." (PMID 33805912, 2021). "Obesity is regarded as a state of low-grade systemic inflammation, where high levels of tumour necrosis factor-α (TNF-α), interlukin-6 (IL-6) and leptin have been observed in obese compared to normal adipocytes." (PMID 34616553, 2021).
Obesity (continued). "Obesity triggers the expression and release of the pro-inflammatory cytokine TNFα from adipocytes and resident macrophages in adipose tissue, where it interferes with insulin signaling and triglyceride metabolism." (PMID 34686752, 2021). "The development of chronic, low-grade systemic inflammation is present early in both T2D and obesity, where pro-inflammatory cytokines are released from M1-type macrophages (TNF-α, IL-6, IL-12, IL-18)." (PMID 33924876, 2021). "ILC2s can indirectly regulate type 1 cytokines such as TNF-α and IL-1β, found in cases of obesity, through influencing M1 macrophage polarization." (PMID 34489979, 2021). "Inflammatory proteins, especially Ccl2 (encoding MCP-1), recruit macrophages into obese adipose tissue and TNF-α further activates the inflammatory cascade, maintaining obesity-induced systemic inflammation." (PMID 34135978, 2021). "Mounting evidence show the elevated TNF-α in the adipose tissue and the lung in high-fat diet induced obesity." (PMID 35082682, 2021). "For the past decades, TNFα has been at the forefront of several studies investigating the patho-biochemistry of chronic, low-grade inflammation that accompanies obesity." (PMID 34576943, 2021). "Obesity-induced inflammation is an important mechanism linking obesity to MetS, and miR-145 stimulates the expression of TNF-α in adipocytes." (PMID 33557426, 2021). "Pediatric populations with obesity tend to follow a similar pattern since a recent study underlined that leptin, IL6, and TNF α serum levels significantly correlate to body mass index in children with obesity." (PMID 34207683, 2021). "Among all the significantly enriched pathways, the TNF signaling pathway is commonly found in obesity and diabetes, whereas the IL–17 signaling pathway and sulfur relay system are common in both obesity and NASH." (PMID 34833079, 2021). "Inflammation related to obesity affects the expression of adiponectin and tumor necrosis factor (TNF)-α in adipose tissue, which leads to the secretion of other proinflammatory cytokines." (PMID 34828628, 2021). "The studies report that obesity is associated with significantly elevated levels of Il-5, Il-10, Il-12, Il-13, IFN-γ and TNF-α." (PMID 34444287, 2021). "In patients with obesity, inflammatory cytokines, such as interleukin (IL)-1, IL-6, and TNF-α, increase and are reported to induce higher IR conditions." (PMID 34959901, 2021). "In the adipose tissue, PD-1 is upregulated in IL-33-activated ILC2s in response to TNF-α, present in high concentrations due to obesity." (PMID 34489979, 2021). "The expression of adiponectin is downregulated in obesity, while several factors, such as leptin, tumor necrosis factor α (TNFα), interleukin (IL)-6, and resistin, are overproduced." (PMID 33671428, 2021). "In obesity, levels of Tumor Necrosis Factor-Alpha (TNF-α) are elevated, and Toll-like receptors (TLRs) are stimulated by excess of fatty acids." (PMID 34677390, 2021). "In obesity, proinflammatory cytokines, such as TNF and IL-6, are produced predominantly by adipose tissue macrophages." (PMID 34201844, 2021). "Obesity is accompanied by chronic inflammation due to an increased production of pro-inflammatory cytokines like TNF-α and IL-1β, which are activated by NF-κB." (PMID 32882776, 2021). "Inhibiting ACSL1 in monocytes suppressed the TNF-α-induced expression of CD11c, which is a highly expressed inflammatory marker on monocytes and macrophages during conditions of obesity." (PMID 34299302, 2021). "The consolidated evidence ascribes a pivotal role to TNF-α in orchestrating obesity-related metabolic dysfunction as shown, in vitro, by the reduced uptake of glucose in hypertrophic adipocytes persistently exposed to TNF-α." (PMID 34680177, 2021). "TNF-α for example, which is increased in patients with obesity, has the potential to inhibit adiponectin production in human adipocytes in vitro while leptin production remained intact." (PMID 33557015, 2021).
Obesity (continued). "Further, both TRAIL and TNF-α are thought to be importer mediators of inflammation of adipose tissue and obesity-related disease." (PMID 33574564, 2021). "To simulate the low-level inflammatory response during obesity, we selected the TNFα concentration of 1 ng/mL for five days in subsequent experiments." (PMID 34650665, 2021). "Obesity is accompanied by excessive ROS, which activates the TNF, NF-κB, and JNK signaling pathways to induce apoptosis and inflammation." (PMID 33531053, 2021). "It has been shown that macrophages from the stromal vascular fraction are also the source of adipose-derived TNF-α and that its increased levels in obesity are due to the increased infiltration of adipose tissue with M1 macrophages." (PMID 34572984, 2021). "Circulating plasma levels of several immuno-modulatory peptides, including TNFα, IL-6, IL-8, IL-10, IL-18 and C-reactive protein, were found to be elevated in human obesity." (PMID 34571976, 2021). "Obesity people is characterized by chronic inflammation and impaired innate immunity with ample production of proinflammatory factors including tumor necrosis factor (TNF-α) and interleukin-6 (IL-6), which also comprised one of risk factors for COVID-19." (PMID 34367067, 2021). "We see the linkage of TNF (tumor necrosis factor) to adiponectin, highlighting the connection of obesity with higher risks of tumorigenesis." (PMID 33805313, 2021). "It is well known that TNFα exerts potent proinflammatory actions in metabolic diseases such as obesity and insulin resistance, with both disorders associated with high risk of developing cardiovascular alterations." (PMID 34502180, 2021). "In a second step, a quasi‐linear association of obesity indices with leptin, CRP, IL‐6, and TNF‐α was investigated." (PMID 33680494, 2021). "Abnormalities in TNF-α signaling and overproduction of TNF-α lead to the development of many diseases, including rheumatoid arthritis, psoriasis, Crohn’s disease, atherosclerosis, sepsis, diabetes, and obesity." (PMID 34946724, 2021). "M1 macrophages which increase with the progression of HFD-induced obesity highly express pro-inflammatory cytokines, including TNF-α, which is considered to be involved in insulin resistance." (PMID 33494317, 2021). "For instance, in a model of Genetic TNF-α−/− mice high-fat diet-induced obesity enhanced phosphorylation of GSK3β and entered β-catenin to the nucleus, thereby, increased the levels of Wnt signaling target genes (C-myc, Cyclin D1, and Axin 2)." (PMID 33827616, 2021). "The increased relative mRNA expression of the pro-inflammatory cytokine TNF-α in adipose tissue of HFD-fed mice once more confirms the increased adipose tissue inflammation in obesity." (PMID 34368213, 2021). "TNF-α is produced by adipocytes and inflammatory cells in response to chronic inflammation, and its serum levels are strictly related to obesity in T2D." (PMID 34557550, 2021). "Leptin induces the expression of TNF-α, IL-6, and IL-1β in adipose tissue cells, contributing to insulin resistance, and is considered one of the links between obesity, insulin resistance, and atherosclerosis." (PMID 33520042, 2021). "These levels of HOMA-IR were accompanied by high levels of circulating TNF-α, which were more increased under obesity conditions." (PMID 34721412, 2021). "Obesity is a chronic low-grade inflammatory condition that stimulates inflammatory cytokine release, such as tumor necrosis factor (TNF-α), interleukin-6 (IL-6), and C-reactive protein (CRP)." (PMID 34258058, 2021). "For example, maternal high-fat diet in a murine model during lactation [postnatal day 1 (P1) to P21] induced an early-onset obesity in the offspring with elevated inflammatory cytokines, such as IL-4, IL-6, IL-13, IL-17A, and TNF-α." (PMID 34211985, 2021). "A link between obesity and inflammation has been established, and specifically the secretion of proinflammatory adipokines such as IL-1β, IL-6, TNF-α, and MCP-1 is increased." (PMID 34356649, 2021).
Obesity (continued). "A well characterized feature of metabolic syndrome, diabetes, and obesity is low-grade, chronic inflammation characterized by elevated circulating levels of interleukin-1β (IL-1β), IL-6, IL-18, and tumor necrosis factor α (TNFα)." (PMID 33503814, 2021). "Obesity was related to the enhanced TNF-α and reduction in local IL-10, which mediated the aromatase and estrogen biosynthesis in mammary adipose tissue, providing novel insight for prevention strategy of post-menopausal obesity-associated BC." (PMID 34350120, 2021). "In the case of IBS with prevailing diarrhea, especially its comorbid course with obesity, cytokine imbalance was observed, which was manifested by a decreased amount of IL-10 in the blood serum and increased levels of TNFα and TGFβ1." (PMID 34621378, 2021). "It was shown more than two decades ago that insulin resistance in obesity was closely related to adipose tissue inflammation, when increased tumor necrosis factor α (TNFα) expression in the adipose tissue of obese rodents and humans was identified." (PMID 34869524, 2021). "Here, we demonstrate that microglial necroptosis plays a pivotal role in obesity-related hypothalamic inflammation, facilitating proinflammatory cytokine production, such as TNF-α and IL-1β." (PMID 34750365, 2021). "In a model of obesity induced with a hypercaloric diet in Sprague Dawley rats, an increase in proinflammatory markers such as IL-1β and TNF-α was also observed along with oxidative stress." (PMID 34336096, 2021). "The expression of cytokines, such as the Tumor Necrosis Factor α (TNFα), Interleukin (IL)-1 (IL-1) and IL-6, is part of the body’s response to obesity-induced metabolic changes during inflammation." (PMID 34726241, 2021). "Other studies showed contradictory results and that obesity was associated with a good prognosis of IBD, including reduced risks of anti-TNF treatment, surgery, and hospitalization." (PMID 34381741, 2021). "Low-grade chronic inflammation, characterised by a higher concentration, in basal levels, of the pro-inflammatory cytokines TNF-α, IL-1β, monocyte chemoattractant protein-1 (MCP-1) and IL-6, is an obesity hallmark." (PMID 33183383, 2021). "An early study determined a link between obesity and inflammation and showed that adipose tissue synthesizes and releases the proinflammatory cytokine TNF-α." (PMID 34572984, 2021). "Visceral fat tissue takes a greater part in obesity and produces highly proinflammatory cytokines, including IL-6, TNF-α, and IL-8, compared to its subcutaneous counterpart." (PMID 34737743, 2021). "In obesity and type 2 diabetes mice, the interactions between TNF-a and IL-6 aggravate oxidative stress and contribute to coronary endothelial dysfunction." (PMID 33171330, 2021). "Our results showed higher plasma levels of IL-6, IL-1β, TNF-α, IL-8, IL-12, and IL-18 in subjects with obesity before bariatric surgery when compared with the postoperative state." (PMID 34108550, 2021). "In metabolic disorders, such as obesity and T2D, coronary endothelial cell function is markedly impaired by high levels of circulating inflammatory mediators (e.g., TNF-α, IL-1β, and IL-6) contributing to insulin resistance." (PMID 34671656, 2021). "Increased ROS has also been linked to many metabolic alterations, such as insulin resistance, decreases in adiponectin, and increased expression of pro-inflammatory cytokines including TNFα and IL-6, all potential markers of obesity and cancer development." (PMID 33926456, 2021). "The increase of proinflammatory cytokines, such as IL-1β, IL-6, TNFα, and MCP1, in adipose tissue during obesity, is the direct cause of insulin resistance." (PMID 34650665, 2021). "It is now well known that obesity is characterized by a state of chronic low-grade inflammation; that is, obesity induces pro-inflammatory cytokines such as tumor necrosis factor-alpha (TNF-α) and IL-6." (PMID 33557015, 2021).